IL16 (interleukin 16)
Diseases named in the same sentence as IL16 in open-access papers (continued):
Sharing a sentence is not in itself a finding about the gene and the disease.
systemic lupus erythematosus (8 papers, 2006 to 2025). An autoimmune multi-organ disease typically associated with vasculopathy and autoantibody production. "In other organs, increased levels and processing of IL-16 is associated with the pathogenesis of delayed type hypersensitivity and autoimmunity, such as in atopic dermatitis, with autoimmune rheumatoid arthritis and lupus." (PMID 16729885, 2006). "Serum IL-16 was observed to be significantly elevated in patients with systemic lupus erythematosus (SLE) relative to healthy controls, and the level of this cytokine was correlated with SLE activity." (PMID 32264927, 2020). "Two genes, TREML4 and IL16, contained meQTL and were also significantly hypomethylated in African American lupus patients." (PMID 33108347, 2020).
atopic dermatitis (7 papers, 2006 to 2025). "Increased serum levels of IL-16 have been associated with atopic dermatitis in children, but are not correlated with severity of the disease." (PMID 17551575, 2007). "Several blood molecules have been investigated in human studies as potential biomarkers of atopic dermatitis, including TARC/CCL17, macrophage-derived chemokine, IL-22, pulmonary and activation-regulated chemokine, sIL-2R, soluble E-selectin, C-reactive protein, and IL-16." (PMID 34677385, 2021).
colitis (7 papers, 2017 to 2025). Inflammation of the colon. "A significant up-regulation of genes encoding the following cytokines and their receptors—Il13, Il16, Il27, Il2rb, Il2rg, Il6r Il10ra, Faslg, Ltb, Osm, Spp1, Tnf, Tnfsf14—was noted in animals with colitis (CβG−)." (PMID 31590413, 2019). "In a mouse model of colitis-associated colon cancer, a macrophage-specific knockout (KO) of gp96 contributes to colitis and tumorigenesis by enhancing the production of inflammatory cytokines, such as IL-17, IL-23, IL-12, IL-16, and IFN-γ." (PMID 41226319, 2025). "Anti–IL-16 mAb treatment significantly reduced signs of disease in an animal colitis model (trinitrobenzenensulfonic acid (TNBS)-induced), such as weight loss, mucosal ulceration, myeloperoxidase activity (P < 0.001), as well as reduced mucosal levels of IL-1β and tumor necrosis factor-α (TNF-α)." (PMID 40529362, 2025). "And a study using the Tetraodon nigroviridis fish model proved that IL-16 can induce colitis by upregulating the expression of peptide transporter 1 (PepT1) in the colon, thereby increasing formyl-methionyl-leucyl-phenylalanine (fMLF) transport, thus triggering downstream inflammatory pathways." (PMID 37228614, 2023). "The expressions of ICAM-1, IL-1β, IL-16, CXCL10, MCP-1, CXCL9, CXCL12, and TIMP-1 were greatly reduced in MSC-EX-treated colitis group compared with those in the PBS-treated colitis group." (PMID 28842625, 2017). "Cytokine protein arrays showed that the levels of several cytokines, including sICAM-1, IL-1β, IL-16, CXCL10, MCP-1, CXCL9, and TIMP-1, were upregulated (≥50-fold) in the colitis-induced PBS-treated group compared with those in the normal healthy control group." (PMID 28842625, 2017).
glioma (7 papers, 2013 to 2022). A benign or malignant brain and spinal cord tumor that arises from glial cells (astrocytes, oligodendrocytes, ependymal cells). "Associations with pre-diagnostic levels of IL-15 and IL-16 and their modification by diagnosis of immune-related conditions support the importance of immune alterations in glioma aetiology years before diagnosis." (PMID 30297770, 2018). "Higher levels of IL-15 and IL-16 were independently associated with lower glioma risks (Ptrend = 0.002 and Ptrend = 0.001); both associations were more pronounced in individuals with prior immune conditions (Pheterogeneity = 0.0009 and Pheterogeneity = 0.031)." (PMID 30297770, 2018). "In addition, one study reported increased proportion of IL-16 expressing macrophages and microglial cells in human astrocytic tumours that correlated with tumour’s grade, while another study found increased risk of glioma with SNPs in IL-16 gene." (PMID 30297770, 2018). "The lack of a main effect of immune-related conditions in our study does not preclude a role for these conditions in the aetiology of glioma insofar as a prior diagnosis of an immune-related condition significantly modified the associations of glioma risk with IL-15 and IL-16." (PMID 30297770, 2018). "In glioma patients, CD68+IL-16+ macrophages in the brain tissue have been identified as the major source of IL-16 expression correlating well with the glioma WHO grade and therefore its malignancy." (PMID 34654395, 2021). "Compared with IL-15, collective evidence for relevance of IL-16 to glioma aetiology is limited." (PMID 30297770, 2018). "The constitutive IL-16 expression has also been found to upregulate in gliomas and prostate cancer." (PMID 24465869, 2014).
Hypertension (7 papers, 2013 to 2024). The presence of chronic increased pressure in the systemic arterial system. "Among them, FI, Hypertension, FG, BMI, HbA1c, 2hGlu, TG, SBP and DBP exhibited prominent associations with increased risk of DR, while IL16, LDL and HDL were significantly associated with lower risk of DR." (PMID 38506069, 2024). "Neutralization of IL-16 ameliorated cardiac fibrosis in the mouse model of Ang II-induced hypertension." (PMID 23894370, 2013). "Treatment with anti-IL-16 neutralizing antibody ameliorated cardiac fibrosis in the mouse model of angiotensin II-induced hypertension." (PMID 23894370, 2013). "The array of systemic changes in CVD-related biomarkers included increased blood levels of hypertension marker aldosterone, elevated FABP3, a biomarker of heart pathology, and significantly increased vascular markers IL-16 and ST2." (PMID 32804947, 2020).
lupus nephritis (7 papers, 2016 to 2025). Glomerulonephritis in the context of systemic lupus erythematosus. "A urine proteome study using unbiased methods identified IL-16 as a marker of the most severe lupus nephritis." (PMID 40529362, 2025). "Using unbiased proteomic approach we and others independently identified IL-16 as a biomarker of severe lupus nephritis, and top-expressed cytokine in skin lesions of lupus erythematosus." (PMID 40529362, 2025). "Also, urinary IL-16 levels have recently been identified as an indicator of kidney tissue inflammation in lupus nephritis." (PMID 37036003, 2023). "Further sub-analyses of lupus nephritis (LN) versus non-LN, demonstrated significantly reduced IL16 expression e.g., in Th1-like and double negative B cell subsets in LN." (PMID 41061119, 2025). "While some urine‐based biomarkers for lupus nephritis, such as urinary T cells, CD163, CD206, or IL‐16 have been defined, the diagnosis of lupus nephritis still relies on an invasive kidney biopsy, and none of the investigated biomarkers have been translated into clinical routine." (PMID 40760840, 2025).
ulcerative colitis (7 papers, 2007 to 2024). An inflammatory bowel disease involving the mucosal surface of the large intestine and rectum. "Increased plasma IL-16 expression in patients with ulcerative colitis is mainly limited to inflammatory areas of the colonic mucosa." (PMID 39044127, 2024). "Some strains belonging to the genus Paraclostridium have been shown to worsen pathogenesis by increasing TNF‐α, IL‐16, IL‐1, and IL‐17 expressions in the mouse‐induced ulcerative colitis model." (PMID 39620016, 2024). "Previous studies have shown that TNFα and IL6 increase in patients with ulcerative colitis, and deletion of TNFα or IL16 reduces CAC in murine models." (PMID 37810110, 2023). "Indeed, patients with ulcerative colitis exhibited very high levels of circulating nucleosomes as compared to patients with WD, but their circulating levels of IL-16 were similar to those of healthy controls." (PMID 17551575, 2007).
Allergy (6 papers, 2010 to 2022). An allergy is an immune response or reaction to substances that are usually not harmful. "The associations of IL-16 with motor activity and allergy in this study clearly add to the concept of this being a pleiotropic cytokine, for which not all the roles have yet been elaborated." (PMID 20534153, 2010). "The IL-16/IL-10 ratios reflected sensitivity to allergy and were associated with S100B levels and oppositional symptoms." (PMID 20509936, 2010). "Third, while across all children the sensitivity to allergy reflected increased levels of IL-16 and IL-10, the latter showed a significant inverse relationship to measures of S100B in the ADHD group." (PMID 20509936, 2010). "But across all subjects IL-16 levels correlated positively with the severity of allergy (r = +0.26, p = 0.04, n = 61)." (PMID 20509936, 2010). "The biological function of IL-16 and its implications in allergic diseases remain to be determined." (PMID 35889925, 2022). "Several studies have shown that IL16 is constitutively expressed in peripheral blood monocytes and that there is a direct link between IL16 expression and apoptosis, and with autoimmune and allergic diseases." (PMID 25613284, 2015). "Children sensitive to allergy showed 15% more IL-16, 32% more IL-13 and similar levels of IL-10." (PMID 20534153, 2010). "IL-16 relationship to oppositional/hyperactive symptoms depended partly on allergy sensitivity." (PMID 20509936, 2010). "c) Decreasing S100B levels in ADHD groups related to decreasing levels of IL-16, but increasing levels IL-10 (independent of age), - where IL-16 and IL-10 correlated with allergy sensitivity." (PMID 20509936, 2010).
depression (6 papers, 2022 to 2025). "IL-16 and other proinflammatory cytokines are associated with elevated depression and neuroticism scores in hepatitis C patients receiving cytokine-based immunotherapy." (PMID 38538641, 2024). "Depressive symptoms and major depressive disorder, anxiety, insomnia and phsychosomatic symptoms, fatigue-fibromyalgia symptoms and melancholia have been found to be associated with circulating levels of IL-16 and activation of Th1 immune response." (PMID 40529362, 2025). "Only four SNV variants were considered to have high penetrance for depression: OGDHL rs2293239, TBX1 rs41298838, IL16 rs201457933, and FBXO15 rs79499419." (PMID 35370858, 2022). "Compared with TBX1, IL-16, and FBXO15, we found that OGDHL was strongly associated with depressive disorders in a range of different aspects." (PMID 35370858, 2022). "We observed that the phenome of depression was best predicted by ACE + NLEs, IL-16, TRAIL (all positively), and sIL-1RA and CCL3 (both inversely)." (PMID 38538641, 2024). "A second study also found that neurocognitive symptoms in patients with depression were positively correlated with the transcription levels of pro-inflammatory factors TNF-α, IL-16, McP-1, McP-2, MIP-1-α, MIP-1 -β, TGF -β, and IFN-β." (PMID 37270510, 2023). "Nonetheless, considering the uncertain relevance of IL-16 and FBXO15 for depressive disorders, we did not prioritize them in the functional investigation." (PMID 35370858, 2022).
heart failure (6 papers, 2013 to 2025). Inability of the heart to pump blood at an adequate rate to meet tissue metabolic requirements. "IL-16 levels help to predict the likelihood of coronary artery events and appear to play a role in the inflammatory and apoptosis pathways underlying incident heart failure." (PMID 38162538, 2024). "Interleukin-16 (IL-16) has also been reported to mediate left ventricular myocardial fibrosis and stiffening in patients with heart failure with preserved ejection fraction." (PMID 40529362, 2025). "Previous studies have reported that interleukin-16 promotes cardiac fibrosis and myocardial sclerosis in heart failure with ejection fraction retention (HFrEF)." (PMID 37334672, 2023). "Since then, IL-16 has been shown to be associated with various inflammatory, allergic or infectious diseases, but the role of IL-16 in the pathophysiology of heart failure has not been previously reported." (PMID 23894370, 2013). "Pathway analysis by ‘Cellchat’ showed that NCAM, IL16, SELL, MK, PARs, SEMA4, CCL, MHC-II pathway were only enriched in the heart failure group." (PMID 37334672, 2023). "Furthermore, inflammatory-related pathways (IL16, CCL, MHC-II) were found to be activated in the heart failure group." (PMID 37334672, 2023).
ischemic stroke (6 papers, 2013 to 2026). A stroke disorder caused by obstruction of blood flow to the brain, due to thrombotic (local blood clot formation) or embolic (due to a blood clot or other material traveling from another site) event. "We found that the rs11556218TG genotype and G allele of IL-16 were associated with significantly increased risks of ischemic stroke (TG versus TT, adjusted OR = 1.88; 95% CI, 1.15–3.07; G versus T, adjusted OR = 1.54; 95% CI, 1.05–2.27, resp)." (PMID 24288444, 2013). "We aimed to examine the relationship between the IL-16 polymorphisms and the risk of ischemic stroke in a Chinese population." (PMID 24288444, 2013). "IL-16, released by activated CD8+ T cells, contributes to the inflammatory response following ischaemic stroke." (PMID 38802464, 2024). "In addition, IL-16 promotes the production of inflammatory cytokines such as TNF-α, IL-1β, and IL-6, which has key effects in immune responses after ischemic stroke." (PMID 35173738, 2022).
prostate carcinoma (6 papers, 2014 to 2023). A carcinoma that arises from epithelial cells of the prostate gland. "For PCa, previous studies reported that IL-1β, IL-4, and IL-16 gene polymorphisms could affect the incidence of prostate cancer." (PMID 36034203, 2022). "Meanwhile, in prostatectomy tumor specimens of prostate cancer patients, the expression of IL-16 is positively correlated with Gleason score and pathological stage, and IL-16 is also highly expressed in other types of tumor cells." (PMID 36034203, 2022). "Two studies did not detect an association between IL-16 and prostate cancer risk, which were consistent with our study." (PMID 36733309, 2023). "Their study suggested that cytokine gene polymorphisms (IL-16 rs11556218 and rs7175701) might not be risk factors for prostate cancer in the central Chinese population." (PMID 36733309, 2023). "No overall association between IL-16 and prostate cancer was detected in Caucasians." (PMID 36733309, 2023). "Moreover, IL-1ra, IL-8, IL-16, and several other interleukins were also researched in prostate cancer, but there were still lacked consistent opinions and a comprehensive evaluation for them in prostate cancer." (PMID 36733309, 2023). "In summary, the present study suggests that cytokine gene polymorphisms, including IL-1β rs16944, IL-4 rs2070874, IL-4 rs2227284, IL-16 rs7175701, and IL-16 rs11556218 may not be risk factors for prostate cancer in a population in central China." (PMID 36034203, 2022). "In prostate cancer, Andrographolide has been known to inhibit cell viability and cell migration by modulating CXCL11, CXCR3, CXCR7, and IL-16 expression." (PMID 30800220, 2019).
Alzheimer disease (5 papers, 2017 to 2023). A progressive, neurodegenerative disease characterized by loss of function and death of nerve cells in several areas of the brain leading to loss of cognitive function such as memory and language. "Regarding these cytokines, there is a reported that association between polymorphisms in IL-16 and IL-2 genes and the risk of late-onset Alzheimer’s disease." (PMID 34302237, 2021). "At present, relatively consistent studies indicate that IL-16 is significantly correlated with the pathogenesis of Alzheimer’s disease (AD)." (PMID 37270510, 2023). "Multiple brain cytokines were elevated in Alzheimer’s disease and vascular dementia: IL-15 and IL-17A were maximally elevated in end-stage Alzheimer’s disease (Braak tangle stage V–VI) whereas IL-2, IL-5, IL12p40 and IL-16 were highest in intermediate Braak tangle stage III–IV disease." (PMID 33723589, 2021). "For many cytokines, (IL-5, IL-2, IL-12p40 and IL-16), however, the level was highest in BSIII–IV disease, suggesting perhaps that the deleterious effects of systemic infection on the brain are likely to be maximal at an early to intermediate stage of Alzheimer’s disease." (PMID 33723589, 2021).
breast tumor (5 papers, 2014 to 2024). "When looking at tissue specificity, our dataset revealed some breast tumor-specific characteristics, as IL-16, as well as some juxta-tumor-specific secreted molecules, as IL-33." (PMID 36539890, 2022). "Our study aimed to elucidate the interplay of ligands and receptors between cells within the breast tumor microenvironment using CellChat, focusing on CXCL, TGFb, VEGF, and IL16 signaling pathways pivotal in intercellular communication." (PMID 38911373, 2024). "Furthermore, Il-16 (2.7-fold) and C-X-C motif chemokine ligand 9 (Cxcl9, ninefold) levels were significantly increased in SRC-3 KD E0771 breast tumors compared to control breast tumors." (PMID 36316775, 2022). "Our analysis not only showed for the first time the presence of IL-16 in breast tumor tissue, but also demonstrated the specificity of IL-16 to the breast tumor microenvironment relative to the non-malignant counterpart." (PMID 36539890, 2022). "However, immune cells also produce Cxcl9, Il-1ra, and Il-16, while it is not clear whether SRC-3 KD breast tumors express these cytokines." (PMID 36316775, 2022).
experimental autoimmune encephalomyelitis (5 papers, 2007 to 2022). An autoimmune demyelinating disease of the central nervous system that is produced experimentally in animals by the injection of homogenized brain or spinal cord in Freund's adjuvant. "This study investigates the correlation of IL-16 expression levels in the CNS with the severity of neuroinflammation and determines the phenotype of cells which produce IL-16 in the CNS of experimental autoimmune encephalomyelitis (EAE) mice." (PMID 34071825, 2021). "The combination of increased levels of IL-16 and caspase 3 activity has been reported in cerebrospinal fluid from patients with multiple sclerosis and experimental autoimmune encephalomyelitis, and is correlated with disease activity." (PMID 17551575, 2007). "Our results also suggest that anti-IL-16 therapy could be administered along with antibiotic treatment for patients with WD, as successfully reported in experimental autoimmune encephalomyelitis." (PMID 17551575, 2007).
leukemia (5 papers, 2014 to 2025). A malignant (clonal) hematologic disorder, involving hematopoietic stem cells and characterized by the presence of primitive or atypical myeloid or lymphoid cells in the bone marrow and the blood. "Similar with our findings, decreased level of IL‐16 were observed after Ibrutinib treatment in those patients with chronic lymphocytic leukemia, emphasizing that IL‐16 is correlated with disease burden and aberrant immune microenvironment in leukemia patients." (PMID 41208700, 2025).
melanoma (5 papers, 2011 to 2024). A malignant, usually aggressive tumor composed of atypical, neoplastic melanocytes. "IL-17A induces the expression of inflammatory cytokines IL-1β, IL-16 and IL-23 in the tumor microenvironment in malignant melanoma." (PMID 36135194, 2022). "The involvement of IL-16 and Jagged 1 in melanoma spheroids enhanced immune-modulator function would thus, be determined in future studies." (PMID 21526207, 2011).